VEGFA (vascular endothelial growth factor A)
Diseases named in the same sentence as VEGFA in open-access papers (continued):
Sharing a sentence is not in itself a finding about the gene and the disease.
non-small cell lung carcinoma (305 papers, 1998 to 2026). A group of at least three distinct histological types of lung cancer, including non-small cell squamous cell carcinoma, adenocarcinoma, and large cell carcinoma. "LINC00941 regulates VEGFA expression by adsorbing mir-877-3p and promotes the progression of non-small cell lung cancer." (PMID 35647035, 2022). "Bevacizumab, an anti-VEGFA mAb, was approved for colorectal cancer treatment in 2004 and has been approved for glioblastoma, non-small-cell lung carcinoma (NSCLC), kidney, cervical, and ovarian cancers to date." (PMID 34332576, 2021). "PPARβ/δ gene expression is upregulated in patients with non-small cell lung cancer and correlated with the expression of VEGFA and COX2." (PMID 24203162, 2014). "Nevertheless, the majority of non-small cell lung carcinomas (NSCLCs) are angiogenic and express vascular endothelial growth factor-A (VEGF), the predominant pro-angiogenic ligand that is exploited by tumours." (PMID 21540863, 2011). "Ivonescimab, a PD-1/VEGFA bispecific antibody, is effective in advanced non-small cell lung cancer, but its efficacy in patients with baseline MPE and complex acquired resistance remains unclear." (PMID 41479892, 2025). "Previous studies proved FOXK2 induced apatinib resistance through VEGFA/VEGFR1 pathway in anaplastic thyroid cancer and mutation of WRN induced apatinib resistance through activating the PI3K/AKT apoptosis-inhibiting pathway in non-small cell lung cancer." (PMID 38402402, 2024). "While inactivation of a single VEGFA isoform is much more complicated task, there is only one published investigation describing ribozyme-mediated specific cleavage of VEGFA-189 in non-small cell lung cancer cells that resulted in attenuation of their malignant potential." (PMID 29888133, 2018). "The TUSC8 gene encodes a non-coding RNA (ncRNA), TUSC8, and this ncRNA reportedly enhances the cisplatin sensitivity of non-small-cell lung cancer cells by regulating vascular endothelial growth factor A (VEGFA), although the involvement of this ncRNA in opioid sensitivity remains unknown." (PMID 37176129, 2023). "In addition, EIF4A3 is overexpressed in non-small cell lung cancer (NSCLC), where it competitively binds to LINC00667 and thereby upregulates expression of its target gene encoding vascular endothelial growth factor A (VEGFA)." (PMID 34458150, 2021). "In non-small cell lung cancer (NSCLC), CAF-secreted VEGFA promotes angiogenesis and affects RNA modifications within tumor cells." (PMID 40176140, 2025). "Most non-small cell lung cancer (NSCLC) cells overexpress VEGFA, and brain-derived neurotrophic factor (BDNF) enhances VEGF-dependent angiogenesis." (PMID 35805939, 2022). "Recently, anlotinib hydrochloride, a new orally administered tyrosine kinase inhibitor, was found to have extensive advantages in treating non-small cell lung cancer by targeting KIT, VEGFA and FGFR1." (PMID 32427575, 2020). "A significant finding is that IL-17A can influence tumor growth and angiogenesis in non-small cell lung cancer despite not affecting VEGFA production." (PMID 38515019, 2024). "First, CAFs can raise m6A activity inside tumor cells without necessarily transferring RNA: in non-small cell lung cancer (NSCLC), CAF-conditioned cues (notably VEGFA) induce tumor-intrinsic METTL3, elevating m6A on RAC3 and driving AKT/NF-κB signaling, invasion, and in vivo growth." (PMID 41280938, 2025).
neovascular age-related macular degeneration (303 papers, 2008 to 2026). "Subsequently, based on the mLP platform, CRISPR-Cas9 mRNA (mLP-CRISPR) was delivered to target vascular endothelial growth factor A (Vegfa) for the treatment of wet age-related macular degeneration in a mouse model." (PMID 41210587, 2025). "For example, in the case of neovascular age-related macular degeneration, the genetic contribution of vascular endothelial growth factor A locus is relatively small, yet VEGF monoclonal antibodies have been remarkably successful at controlling disease." (PMID 38272457, 2024). "Applications of mLP-CRISPR that targeted vascular endothelial growth factor A (Vegfa) in a mouse model of age-related wet macular degeneration reduced Vegfa expression by 44% and reduced choroidal neo-vascularization after a single subretinal injection." (PMID 37008065, 2023). "In one study, the authors used these hybrid particles to target vascular endothelial growth factor A (Vegfa) to suppress aberrant development of blood vessels in a mouse model of wet age-related macular degeneration." (PMID 35955895, 2022). "The increasing expenditure for ophthalmic preparations has mainly been attributed to the introduction of the vascular endothelial growth factor A (VEGF-A) antagonist ranibizumab to treat neovascular age-related macular degeneration." (PMID 20478043, 2010). "The management of neovascular age-related macular degeneration (nAMD) has been transformed by the introduction of agents delivered by intravitreal injection which block the action of vascular endothelial growth factor-A (anti-VEGF agents)." (PMID 18854025, 2008). "Another VEGFR-targeting fusion protein composed of VEGFR1 peptide antagonist and elastin-based polypeptide inhibited VEGFA-triggered angiogenesis in vitro, and suppressed choroidal neovascularization in a wet age-related macular degeneration mouse model in vivo." (PMID 40841907, 2025). "Many patients with wet age-related macular degeneration do not respond well to anti- vascular endothelial growth factor A (VEGFA) therapy for choroidal neovascularization (CNV), and the efficacy of anti-VEGFA decreases over time." (PMID 32917003, 2020).
COVID-19 (299 papers, 2020 to 2026). A disease caused by infection with severe acute respiratory syndrome coronavirus 2. "A prospective case–control study showed that VEGFA in women with COVID-19 was associated with some adverse outcomes." (PMID 35464051, 2022). "VEGFA contributes to increased vascular permeability during various stages of inflammation, and its presence has been associated with the development of neurological symptoms in COVID-19 patients." (PMID 37764186, 2023). "Thus, three targets (RELA, TNF, and VEGFA) linked to the MAPK signaling pathway might be promising targets for use against COVID-19." (PMID 35678652, 2022). "The significance of this phenomenon in COVID-19 pathogenesis is highlighted by the finding of elevated VEGFA levels in the lungs of patients who died from the disease." (PMID 40431631, 2025). "Numerous studies have reported vascular endothelial growth factor A (VEGF-A) has a significant impact on the pathophysiology of COVID-19." (PMID 40075026, 2025). "Increased VEGFA is associated with inflammatory-related chronic pain in a variety of conditions and substantially lower levels of VEGFA are reported in the sera of asymptomatic compared to symptomatic COVID-19 patients." (PMID 38991709, 2024). "By contrast, transcriptomic sequencing of transmigrated human neutrophils sampled from nasopharyngeal swabs or broncho-alveolar fluid in COVID-19 revealed upregulation of the HIF1α downstream target gene VEGFA, indicating successful HIF1α protein translation." (PMID 39469705, 2024). "VEGFA is primarily involved in angiogenesis and vascular permeability and is significantly increased in patients with COVID-19, wherein it correlates with the disease severity." (PMID 37274117, 2023). "Gene set enrichment analysis of DEGs showed upregulation of IL-18 (P < 0.001), TNF (P < 0.0001), and VEGFA-VEGFR2 signaling pathways (P = 0.002) in COVID-19 subjects." (PMID 36881624, 2023). "MLCs demonstrated an up-regulation of fibrosis-associated genes, such as VEGFA and HIF1A in PPASC compared to severe COVID-19." (PMID 38259488, 2023). "Seven out of the 16 known cytokine markers (including IL1A, IL1R1, CCL2, IL6, IL10, CXCL10, and VEGFA) were less pronounced in KD than in severe COVID-19 patients compared to FC and HC, respectively." (PMID 36159873, 2022). "We observed that CXCL8 (AUC 0.98) and VEGFA (AUC 0.94) were particularly good at predicting COVID-19 outcomes within hematologic cancer patients, while CXCL8 (AUC 0.89) and IL-6 (AUC 0.88) were good predictors for solid tumor patients." (PMID 36700209, 2022). "Mon HLA and Mon CD14 inside Delta samples differ in expression for the cytokine panel (CCL3, VEGFA, CCL5, CCL4, CXCR4, IL7R, CXCL8, and PF4) that have been found associated with COVID-19 severity and mortality." (PMID 36230912, 2022). "The clinical study showed that MMP-1 and vascular endothelial growth factor A (VEGF-A) were significantly elevated in hospitalized COVID-19 patients when compared to mild/moderate cases." (PMID 35741101, 2022). "For example, the increase in IL-2, MMP9, and VEGFA is related to the mortality of COVID-19 patients." (PMID 34803696, 2021). "The levels of VEGFA involved in coagulopathy and thrombosis are significantly elevated, indicating that the condition of hypoxemia and inflammation exist in COVID-19 patients." (PMID 35069542, 2021). "Of these age-correlated proteins, six had been also associated with COVID-19 severity: HGF and CXCL9 shown the highest coefficients while IL10RB, VEGFA, IL-6 and TNF showed low albeit significant correlation (r < 0.30)." (PMID 34335580, 2021). "Significantly up-regulated levels of cytokines and chemokines including IL1-β, IL1RA, IL10, IL9, IL8, IL7, basic FGF2, GCSF, GMCSF, IFNγ, IP10, MCP1, MIP1α, MIP1β, PDGFB, TNFα, and VEGFA in blood, have been confirmed in COVID-19 patients." (PMID 33041797, 2020).
COVID-19 (continued). "This phenomenon may be significant in COVID-19 pathogenesis, as elevated VEGFA levels have been observed in the lungs of deceased COVID-19 patients." (PMID 39744674, 2024). "ScRNA-seq of BAL samples identified 5 transcriptionally distinct neutrophil clusters in severe COVID-19 patients, particularly those expressing VEGFA, chemokine receptors, S100 proteins, and IFNs, which differentially impact COVID-19 severity depending on interactions with other immune cells." (PMID 37828990, 2023). "Further studies are needed to determine the mechanism of VEGFA in humans and whether this effect is valuable for patients recovering from COVID-19." (PMID 37457560, 2023). "Notably, a report indicated that vascular endothelial growth factor A (VEGFA) antagonized by angiotensin-converting enzyme 2 (ACE2) that is upregulated by COVID-19 infection because COVID-19 inhibits the expression of ACE2." (PMID 35678652, 2022). "The other two targets (TNF and VEGFA) that are directly related to the MAPK signaling pathway might be important targets for creating synergistic effects against COVID-19." (PMID 35678652, 2022). "In another study, the comparison between the levels of inflammatory factors among hospitalized COVID-19 patients exhibited a positive correlation between serum levels of VEGFA and MMP1, suggesting that MMP1 has a critical role in tissue remodeling and vascular permeability." (PMID 35893698, 2022). "MiRNAs that were downregulated in serum of COVID-19 patients mainly target genes promoting angiogenesis (e.g., VEGFA, ANGPT2, COL4A1, FGF2, ZEB1), apoptosis, autophagy, stress response (e.g., ATG12, ATG14, ATG2B, SOD2, TXNIP), and inflammation (e.g., CXCL9, CXCL10, IL1R1, TNF)." (PMID 36032130, 2022). "Systemic inflammation in COVID-19 patients is a participant effector that magnifies vascular pathology, as it includes the pro-coagulant mediators IL-6 plus IL-6R, which induce the vascular-permeability effector VEGFA." (PMID 32629875, 2020). "These miRNAs target several pro-inflammatory cytokine and chemokine genes (e.g., TNF, CCL2, CXCL9, CXCL10, IL10, VEGFA) as well as cytokine and chemokine receptors and transduction factors (IL1R1, IL2RA, IFNAR2), reported as upregulated and associated with mortality in COVID-19 patients." (PMID 36032130, 2022). "Furthermore, TNF and VEGFA, which exhibited higher degree values in target prediction and network construction, may also play significant roles in Danshen's therapeutic effects against COVID-19." (PMID 38834599, 2024). "The signaling network involving TLR4 and VEGFA in COVID-19 ARDS is more complex than in pneumonia and shows additional activating effects of downregulated miR-150-5p and miR-126-3p on VEGFA." (PMID 36776845, 2023). "VEGFA and its ligand expression was minimal in CD14+ and CD16+ monocytes in the severe COVID-19 but was over 40% in dendritic cells." (PMID 38259488, 2023). "Elevations in the EGF, FGF2, VEGFA, sVEGFR1, sVEGFR2, sVEGFR3, PDGFAA, PDGFABBB and sEGFR repair factors have been observed in patients with COVID-19." (PMID 36142255, 2022). "The therapeutic efficacy of SHXP against COVID-19 is likely mediated via the regulation of 4 targets, namely, IL6, IL10, VEGFA, and TNF." (PMID 34941025, 2021).
COVID-19 (continued). "In summary, amygdalin is a candidate compound for COVID-19 treatment by regulating IL6, SRC, MAPK1, EGFR and VEGFA by way of the PI3K-Akt signalling pathway, VEGF signalling pathway and MAPK signalling pathway." (PMID 34908920, 2021). "Amygdalin is a candidate compound for COVID-19 treatment by regulating IL6, SRC, MAPK1 EGFR and VEGFA to involve in PI3K-Akt signaling pathway, VEGF signaling pathway and MAPK signaling pathway." (PMID 34908920, 2021). "Amygdalin is a candidate compound for COVID-19 treatment by regulating IL6, SRC, MAPK1 EGFR and VEGFA to involve in PI3K-Akt signalling pathway, VEGF signalling pathway and MAPK signalling pathway." (PMID 34908920, 2021). "In the delayed pattern at seven days after admission for COVID-19, significant differences were appreciated in serum levels of CD83, KRLD1, VEGFA, NCR, TNFSR24, PD-L2, and IL-12." (PMID 34177897, 2021). "Also in the lung, intussusceptive angiogenesis in COVID-19 has been demonstrated, accompanied by an upregulation of NRP1, NRP2, and VEGFA, in partial agreement with our own findings of NRP1 and NRP2 protein and transcript expression in the lung." (PMID 41159753, 2025). "Interestingly, we observed upregulation of VEGF specifically in MLCs in PPASC compared to controls, but the patterns of up-regulation of VEGFA were more obvious when compared with severe COVID-19." (PMID 38259488, 2023). "Further, VEGFA levels significantly lowered in Group A. In Group A, we also observed PT/INR significantly increased within normal limits which is also an indicator of AV having preventive effects on thrombotic outcomes of hypoxia and COVID-19." (PMID 38049897, 2023). "Age corelated with CXCL9 (r = 0.409) and VEGFA (r = 0.312, all p < 0.05) significantly but did not correlate with any other inflammatory parameters or parameter related to oxidative stress in COVID-19 patients." (PMID 37832397, 2023). "Moreover, inhibition of the other two targets (TNF and VEGFA) related to the MAPK signaling pathway contribute to anti-proinflammation and anti-vascular permeability against COVID-19." (PMID 35678652, 2022). "Several mediators such as Tie-2, VEGFA, IL-17D, IL-3, GM-CSF, IL-1α, IL-5, Eotaxin 3, IL-12p70 and IL-13 were not significantly different between COVID-19 and control subjects (data not shown)." (PMID 36116160, 2022). "A recent study showed that VEGFA, not conventional inflammatory cytokines, was the most unambiguously elevated inflammatory factor in hospitalized COVID-19 patients." (PMID 35295341, 2022). "Some genes that may be related to severe COVID-19 pathophysiology and are good candidates for experimental investigation include PRKG1, ACE, CFB, CRP, CTNNB1, EGFR, and VEGFA." (PMID 35794133, 2022). "Therefore, amygdalin is a candidate compound for COVID-19 treatment by regulating IL6, SRC, MAPK1, MAPK3, VEGFA and EGFR." (PMID 34908920, 2021). "The progress of COVID-19 from mild illness to severe form depends on the circulatory levels of inflammatory cytokines and chemokines such as IL-7, IL-8, IL-9, IL-10, GCSF, GMCSF, TNFα, and VEGFA." (PMID 34786427, 2021). "In addition, we provided several potential targets for COVID-19 AKI treatment, mainly IL6, VEGFA and RELA, which may help to develop new therapeutic strategies." (PMID 37274117, 2023). "Furthermore, a positive correlation was found between the cMono Phenograph clusters specific to severe COVID-19 (clusters 2, 9, 10, and 18) and the soluble immunosuppressive factors IL-10, TGF-β, and VEGFA, as well as with AREG, the latter known to be involved in tolerance and tissue repair." (PMID 33479167, 2021).
COVID-19 (continued). "Microthrombi-positive versus microthrombi-negative COVID-19 comparisons yielded 4 tier 1 targets: PIP5K1A, STAT3, and VEGFA in fibroblasts and CSNK1A1 in pericytes." (PMID 34905515, 2022).